MIR1908 (microRNA 1908)
Synonyms: hsa-mir-1908; MIRN1908; mir-1908
Gene: MicroRNA gene on chromosome 11 (61,815,161 to 61,815,240, reverse strand). Ensembl gene ENSG00000284416.
Diseases named in the same sentence as MIR1908 in open-access papers:
MIR1908 is named in the same sentence as 4 diseases in open-access papers, as found by Europe PMC text mining. Sharing a sentence is not in itself a finding about the gene and the disease. The quoted sentences say what the papers report.
bipolar disorder (1 paper, 2023). A disorder of the brain that causes unusual shifts in mood, energy, activity levels and the ability to carry out day-to-day tasks. "The MIR1908 gene (which gives rise to both miR-1908-5p and miR-1908-3p from different arms of its pri-miRNA hairpin) has been highlighted as a potential risk factor for bipolar disorder in gene-based association analyses of GWAS data." (PMID 37471622, 2023).
prostate carcinoma (1 paper, 2017). A carcinoma that arises from epithelial cells of the prostate gland. "MIR1908 was also found decreased expression level in prostate cancer whose target genes were found expressing in both prostate tumor and normal tissues." (PMID 29190897, 2017). "Besides, MIR1908 was a potential biomarker for prostate cancer patients according to our result." (PMID 29190897, 2017).
prostate tumor (1 paper, 2017). "The target genes of MIR1908 were predicted and were found transcribed actively in prostate tumor tissues and normal prostate tissues." (PMID 29190897, 2017). "MIR1908 showed lower level in prostate tumor tissues in our discovery cohort and the distribution plot were provided." (PMID 29190897, 2017).
MIR1908 also shares sentences with these, for which no sentence is quoted: tumor (1 paper).